IL22 (interleukin 22)
Diseases named in the same sentence as IL22 in open-access papers (continued):
Sharing a sentence is not in itself a finding about the gene and the disease.
psoriasis (continued). "Dendritic cells and macrophages in the dermis of psoriasis produce IL-23, which induces the activation of Th17 cells and γδ T cells and the release of inflammatory cytokines, such as IL-17A, IL-17F, IL-22, IL-6 and tumor necrosis factor-α (TNF-α)." (PMID 40303403, 2025). "The inflammatory cytokines IL-17, IL-22, and IL-9 are generated by these cells and play a role in the development of psoriasis." (PMID 40690118, 2025). "An in vitro model of psoriasis was established by stimulating keratinocyte HaCaT with a mixture of five pro-inflammatory cytokines (IL-17 A, IL-22, IL-1α, oncostatin M, and TNF-α) (M5)." (PMID 40197419, 2025). "The pathogenic role of CD8+ T cells in psoriasis, characterized by the release of cytokines such as IL17A and IL22, has been extensively elucidated." (PMID 41162356, 2025). "In psoriasis, curcumin exhibits its anti-inflammatory effects by reducing the expression of cytokines such as interleukin-17A (IL-17A), interleukin-17F (IL-17F), interleukin-22 (IL-22), IL-6, IL-1β, and TNF-α, and by inhibiting NF-κB activation." (PMID 40718452, 2025). "Especially T helper cells, such as Th17 and Th22 which secrete the cytokines IL-17 and IL-22 play an essential role in psoriasis." (PMID 40678130, 2025). "In the epidermis of a mouse model caused by IMQ or psoriasis patients, the expression of cytokines such as TNF-α, IL-23, IL-17, and IL-22 is very high." (PMID 40343294, 2025). "SPRR2C expression was significantly upregulated in psoriasis skin samples and in vitro cellular lines in response to IL-22 stimulation through the miR-330/STAT1/S100A7 axis." (PMID 40725772, 2025). "Several interleukins including IL-17A, IL-22, IL-23, IL-36γ, IL-6, and IL-1β have emerged as the potential biomarkers of subclinical inflammation and treatment resistance in psoriasis." (PMID 40731810, 2025). "Epidermis models based on Ker-CT_STAT3 responded to IL-22 with stronger expression of the psoriasis marker S100A7, with more pronounced acanthosis and with an increased metabolic activity compared to the wild-type cell line Ker-CT." (PMID 40678130, 2025). "It was already reported that the levels of IFN-γ-secreting Th1 cells and IL-17/IL-22-secreting Th17 cells increase in patients who developed TNF-α-inhibitor-induced psoriasis." (PMID 40709177, 2025). "The stimulation with cytokines IL-17 and IL-22 affected the epidermal stratification and induced expression of psoriasis protein markers in the epidermis models." (PMID 40678130, 2025). "Notably, the characteristic enrichment of IL-17, IL-22 and IL-36 in PN (versus AD) may underlie its clinical overlap with psoriasis, a mechanism validated in our PN-like model through GSVA demonstrating robust Th17/Th22 responses and IL-36 pathway activation in lesional skin." (PMID 41229431, 2025). "As known, IL-22 is a critical cytokine in psoriasis via triggering pathological keratinocyte proliferation, and it also plays a role in the pathogenesis of AD by promoting epidermal barrier disruption and pruritus." (PMID 40309262, 2025). "The mRNA of IL-22 is expressed at higher levels in skin lesions of patients with psoriasis than in healthy individuals." (PMID 40861543, 2025). "ILCs are also major sources of Th17 cytokines such as TNF-α, IL-17, and IL-22, indicating that ILCs and Th17 cells work together through innate immune responses in psoriasis." (PMID 41376622, 2025). "Dendritic cells, T cells, activated keratinocytes, nuclear factor kappa B (NF-κB) transcription factor, IL-23, IL-21, IL-22, and IL-17 are some of the important immune-related elements involved in the pathophysiology of psoriasis." (PMID 39846685, 2025). "Molecular docking studies targeted psoriasis-related proteins (IL-17, IL-22, IL-23, JAK2, MAPK2, NF-κB, STAT3), revealing strong binding affinities for rutin and quercetin, the extract’s dominant bioactives." (PMID 40806422, 2025).
psoriasis (continued). "A similar population of DCs, that express IL-23p19, TNF-a, and iNOS, is called slan (6-sulfo LacNAc) DCs (slanDCs) and contributes to psoriasis by producing IL-17 and IL-22." (PMID 38642273, 2024). "It was reported that pro-inflammatory cytokines and mediators such as IL-17A, IL-22, IL-23, IL-6, IL-1β, and p65 play an important role in the development and maintenance of psoriasis." (PMID 39296901, 2024). "Following that, it was shown that psoriatic lesions consist of psoriasis-specific tissue-resident memory T lymphocytes which induce IL-17 and IL-22." (PMID 38683749, 2024). "This infiltration causes an enhanced expression of inflammatory cytokines that are central to psoriasis pathogenesis, such as IL-17, IL-22, and IFN-γ." (PMID 38929716, 2024). "While Th17 differentiation is induced by IL-6 and TGF-β, IL-23 is essential for Th17-cell function and production of key cytokines in psoriasis, such as IL-17A, IL-17F, IL-22, and TNF- α." (PMID 38731900, 2024). "The ASIC3 knockdown also lessened production of psoriasis-related cytokines, mainly IL-17, IL-22, and IL-23." (PMID 38902277, 2024). "Circ_0024028 is a circular RNA highly expressed into psoriasis lesions and IL-22 stimulated HaCaT cells." (PMID 38827737, 2024). "Another study on psoriasis in IL-22/LPS-stimulated HaCaT cells and psoriasis mice model showed another lncRNA effect, non-coding RNA activated by DNA damage (NORAD) lncRNA increase in cells decreased miR-26a and its inhibitory effects on cell proliferation." (PMID 38958690, 2024). "Both dendritic cells and keratinocytes in psoriasis revealed an overproduction of IL-23 in Extracellular Immunity, subsequently activating Th17 cells in the dermis to generate IL-17A and IL-22." (PMID 38612783, 2024). "No or statistically insignificant differences were observed between psoriasis patients and healthy controls for interleukin-12 (IL-12), interleukin-17a (IL-17a), interleukin-22 (IL-22), and interleukin-23 (IL-23)." (PMID 38668313, 2024). "Patients diagnosed with psoriasis exhibited markedly elevated levels of IL-22 compared to those observed in healthy individuals." (PMID 39195286, 2024). "Dysregulated γδT17 cell activation can lead to the overproduction of IL-17 and IL-22 and the development of inflammatory diseases, including psoriasis." (PMID 38348035, 2024). "AD models can be generated by adding TH2 cytokines such as IL-4 and IL-13, and TNF-α, whereas psoriasis models are induced by treating skin models with cytokine cocktails based on IL-17, IL-22 and TNF-α." (PMID 38251799, 2024). "The Th22 inflammatory cytokine IL-22, a major player in psoriasis pathology, activates JAK proteins TYK2 and JAK1." (PMID 39337637, 2024). "This inhibition resulted in a significant decrease in key inflammatory cytokines (Il1b, Il6, Il12b, Il17a, Il22, and Tnf) that are critical in psoriasis’ pathogenesis." (PMID 39335596, 2024). "Type 1 IFN signaling is associated with increased Th17 polarization in autoimmune diseases like psoriasis and systemic lupus erythematosus, resulting in the production of IL-22 by Th17 cells." (PMID 38298829, 2024). "The mechanism by which oral exposure to FB2 aggravates psoriasis appears to be an increase in IL-17 and IL-22 production in local LNs." (PMID 39063102, 2024). "In contrast, there is growing evidence that γδT cells contribute to psoriasis development as a primary source of IL-17 and IL-22 in skin lesions." (PMID 38348035, 2024). "In general, proinflammatory cytokines and factors stimulating proliferation in psoriasis are produced mainly by T cells (IL-17, IL-21, IL-22, IFN-γ), DCs (TNF-α, IL-6, IL-20, IL-23, NO), and KCs (antimicrobial peptides (AMPs), IL-20, chemokines)." (PMID 38642273, 2024). "Particularly, among activated T cells, Th1 cells produce IFN-γ, which activates macrophages, and Th17 cells release IL-17A, IL-17E, IL-17F, and IL-22, which play a role in the pathogenesis of psoriasis." (PMID 39765869, 2024).
psoriasis (continued). "IL-17 also upregulates the level of psoriasis autoantigens which is potentiated by the vitamin D3 and IL-22." (PMID 38642273, 2024). "In psoriasis patients and mouse psoriasis models, Th17 cells highly express AhR, and IL-22 production by Th17 cells has been found to be dependent on AhR." (PMID 39296901, 2024). "TNF‐α, IL‐1β, IL‐23, IL‐17, IL‐22, Cox2, and iNOS are all inflammatory cytokines involved in the pathogenesis of psoriasis, and CXCL1, CXCL8, and CCL20 are antimicrobial peptides and chemokines produced by keratinocytes." (PMID 38967379, 2024). "The release of IL-22 exacerbates the inflammatory status of psoriasis skin, and in this study, all TEs significantly reduced their expression." (PMID 38542915, 2024). "This canonical signaling pathway is integral to IL-22-induced keratinocyte proliferation and migration in psoriasis." (PMID 38892253, 2024). "In psoriasis, even in remission, they become a source of important inflammatory cytokines such as IL-17A and IL-22." (PMID 39063202, 2024). "Specifically, Ligilactobacillus and Anaeroplasma are positively correlated with various psoriasis-related factors such as IL-6, IL-17A, IL-22, and IL-23, while Rikenella, Alistipes, and Mucispirillum are negatively correlated with them." (PMID 39170985, 2024). "The neolipid antigens were subsequently recognized by lipid-specific CD1a-reactive T cells and induced the production of IL-22 and IL-17A in psoriasis patients." (PMID 38481799, 2024). "When psoriasis occurs, overexpression of pro-inflammatory cytokines such as IL-1, IL-22, and IFN-γ leads to hyperproliferation of keratin-forming cells." (PMID 38542915, 2024). "Results showed that γδT cells produce most IL-17 and IL-22 in murine psoriasis models before overt clinical manifestations appear." (PMID 38348035, 2024). "These cells, under the influence of IL-1β and IL-23 stimulation, produce -IL-17 and IL-22, which in turn constitute an important element in the pathogenesis and development of psoriasis." (PMID 39063202, 2024). "Baseline serum IL-17A, IL-17F, and IL-22 levels were shown to be higher in patients with moderate-to-severe psoriasis than in healthy controls." (PMID 39114670, 2024). "Elevated IL-22 expression in both the skin and peripheral blood of patients with psoriasis compared with that of healthy individuals underscores its involvement in the disease." (PMID 38892253, 2024). "IL-17 drives disease pathogenesis by activating psoriasis-related genes in keratinocytes via IL-22, IL-19, and IL-36 to increase epidermal hyperplasia and produce more antimicrobial peptides, including LL-37/cathelicidin." (PMID 39595528, 2024). "IL-22 is a member of the IL-10 family and is significantly elevated in the serum and lesions of patients with psoriasis." (PMID 38892253, 2024). "The conditional rescue of ASIC3 in NaV1.8Cre mice led to more severe epidermal thickening and Ki67 cell proliferation, as well as higher production of psoriasis-related cytokines, IL-17, IL-22, and IL-23, compared to the ASIC3 knockdown mice." (PMID 38902277, 2024). "Innate lymphoid cells (ILCs) and γδ-T cells, alongside mast cells and neutrophils, also significantly contribute to psoriasis development by releasing substantial levels of IL-17 and IL-22." (PMID 38929716, 2024). "In an in vitro model using IFN-γ/IL-17A/IL-22-stimulated HaCaT cells, leucosceptoside A effectively mitigated psoriasis-related inflammation by suppressing the PI3K/AKT signaling pathway." (PMID 38892253, 2024). "Psoriasis is largely driven by T helper (TH) 1 (TH1) and TH17 cells with the involvement of IL-17A, TNF-α and IL-22, whereas AD is associated with infiltration of TH2 cells in particular." (PMID 38251799, 2024). "The activated JAK-STAT signaling pathway up-regulates the expression of ILs, such as IL-6, IL-17, IL-22, and INF-c, thus causing skin diseases, such as atopic dermatitis and psoriasis." (PMID 38731895, 2024).
psoriasis (continued). "In a mouse model of skin inflammation induced by imiquimod, the anti-psoriasis effect of tea extract was evaluated by measuring its inhibition of several pro-inflammatory cytokines such as IL-1, IL-6, IL-22, FN, IFN-γ, and TNF-α." (PMID 38542915, 2024). "In the case of the psoriasis model, a TH17-associated cytokine cocktail (IL-17A and IL-22) was used, and in the case of the AD model, a TH2-associated cytokine cocktail (IL-4, IL-5 and IL-13) was used." (PMID 38251799, 2024). "In psoriasis, moreover, the cytokines IL-17, IL-22, TNF-α and IFN-γ promote the secretion of antimicrobial peptides (AMPs) such as human β-defensins and the cathelicidin LL-37 (encoded by CAMP) by keratinocytes." (PMID 38251799, 2024). "Gradually, growing evidence suggests that the IL-23/Th17 axis and IL-22/Th22 pathway play critical roles in psoriasis." (PMID 37942312, 2023). "The ability of IL22 to induce adenoside monophosphates and strongly stimulate the proliferation of keratinocytes agrees with the clinical presentation of psoriasis." (PMID 37176138, 2023). "IL-23 receptors are also be able to be induced by ROR-γt, leading to a Th17 polarization and production of IL-17A and IL-22, which further promote psoriasis." (PMID 37270497, 2023). "In psoriasis patients compared with healthy individuals, ILC3s are increased in skin lesions and blood and represent an important source of IL-22 that contributes to the pathogenesis of psoriasis." (PMID 36637514, 2023). "Th17-derived proinflammatory cytokines (IL-17A, IL-17F, IL-21, IL-22, and IL-26) have a critical role in the pathogenesis of several autoimmune diseases such as psoriasis, multiple sclerosis, rheumatoid arthritis, and inflammatory bowel disease." (PMID 37495626, 2023). "Increased ILC3s after human skin grafting can induce psoriasis, with 78% of ILC3s expressing IL-22 and 7–13% ILC3s expressing both IL-17 and IL-22." (PMID 37395809, 2023). "In psoriasis, it has been shown that selective inhibition of IL-23 blocks downstream production of IL-17A and IL-22 by Th17 and other cells." (PMID 37715294, 2023). "On the other side, besides secreting IL-17, Th17 cells can also release TNF-α, IL-6, IL-21, and IL-22, participating in the development of psoriasis." (PMID 37942312, 2023). "Aryl hydrocarbon receptor (AHR)-dependent responses were also evaluated in CD69-deficient mice in a model of psoriasis induced by IL-23, as these mice developed mild psoriasis and showed reduced IL-22 and STAT3 levels." (PMID 37223078, 2023). "CD8+CD103+ TRM cells release psoriasis-associated cytokines such as IFN-γ, IL-17A, and IL-22, while CD4+CD103+ TRM cells and CD8+CD103- TRM cells don’t secrete these cytokines." (PMID 37942312, 2023). "Tumor necrosis factor-alpha (TNF-α), interleukin-1 alpha (IL-1α), interleukin-17A (IL-17A), interleukin-22 (IL-22), and oncostatin M (OSM) are closely associated with the pathogenesis of psoriasis." (PMID 36999136, 2023). "Studies comparing patients afflicted with psoriasis to a control group show a significantly higher IL-22 expression in the psoriasis group." (PMID 38067173, 2023). "During the onset of psoriasis, external stimuli trigger the recruitment and activation of immune cells to secrete cytokines such as IL-17, IL-22, TNF-α, and INF-γ, which promote keratinocyte proliferation." (PMID 37762693, 2023). "Baicalin was found to mitigate the common symptoms of psoriasis, such as epidermal thickening, erythema, and desquamation induced by IL-17A, IL-22, and IL-23." (PMID 37371141, 2023). "Upon activation of the mTOR network, diverse cytokines and other pro-inflammatory mediators, such as IL-6, CXCL8, and IL-22, are released, which increases the inflammation and proliferation of cells commonly seen in psoriasis." (PMID 37371141, 2023). "AOA improved psoriasis-related symptoms by suppressing Th17-mediated cytokines, such as IL-17 and IL-22, and by reducing antimicrobial peptides in a psoriasis treatment model." (PMID 37649889, 2023).
psoriasis (continued). "Increased Th17 cells and related cytokine expression such as IL-17and IL-22 have been reported in psoriasis patients." (PMID 37686332, 2023). "KLF6, which has been reported to strongly associate with T cell activation in psoriasis, was also found to be expressed at higher levels in CD1a-GAS reactive IL-22-producing T cells." (PMID 37267382, 2023). "Inhibition of BET proteins has been shown to decrease the expression of RORC, IL-17A and IL-22, all of them important psoriasis pro-inflammatory factors, representing a potential new therapy for psoriasis." (PMID 37628670, 2023). "Then, to investigate the mechanism of TGF-β induction, we stimulated healthy keratinocytes (NHEK) in vitro with a number of cytokines characterizing the psoriasis microenvironment including IL-1β, IL-6, IL-17A, IL-19, IL-22, IL-23, IL-26, and IFN-γ." (PMID 37391412, 2023). "Patients with psoriasis had significantly elevated frequencies of IL-22 producing circulating GAS-responsive CD1a-reactive T cells." (PMID 37267382, 2023). "Serum cytokines, including TNF-α, IFN-γ, IL-2, IL-6, IL-22, and IL-23, are primarily produced by Th1 and Th17 cells and have emerged as potential biomarkers for psoriasis." (PMID 38239345, 2023). "Many signals (e.g., DAMPs, CCN1, and IL-22) in psoriasis can activate the JNK pathway in keratinocytes." (PMID 38008779, 2023). "An analog of vitamin D 1α,25-dihydroxyvitamin D3-3-bromoacteate has been shown to inactivate Akt and eventually mTOR, resulting in decreased production of IL-22 and psoriasis-like characteristics." (PMID 37371141, 2023). "It is of interest that IL-22 is also elevated in wounds, and psoriasis lesions can show the Koebner phenomenon where disease develops at sites of skin trauma." (PMID 37267382, 2023). "Considering the significant role of IL-22 in psoriasis pathogenesis, we added IL-22 (25 mM) to HaCaT cells treated with or without SFN." (PMID 38007430, 2023). "We determined susceptibility of KC to VV and HSV-1 infection after exposure to representative cytokines prevalent in diverse inflammatory cutaneous diseases: IFNγ (lupus/AD; type 1), IL-4 and IL-13 (AD; type 2), IL-22 and IL-17A (psoriasis/AD, type 3)." (PMID 37298195, 2023). "We also treated HMEC-1 cells with psoriasis-related cytokines such as IL-17A, IL-22, IL-25, IFN-γ, TNF-α, and, VEGF-A, and among them, IFN-γ significantly upregulated the expression and secretion of IGFBP7 in HMEC-1 cells." (PMID 36917196, 2023). "In psoriasis patients, IL-22 acts synergistically with IL-17, TNF-α and other cytokines to maintain the inflammatory response in psoriasis." (PMID 37270497, 2023). "Since this cytokine show synergy with TNF-α, IL-1α, IL-17A, and IL-22 in production of antimicrobial peptides, it is considered to be involved in pathogenesis of psoriasis." (PMID 37881433, 2023). "Earlier, IL-23 secreted by these cells was shown to stimulate γδ T cells to secrete IL-17A, IL-17F, and IL-22 in psoriasis." (PMID 36645209, 2023). "In accordance with previous studies, both IL-22 and IL-23 strongly induced hBD-2 expression, thus giving a clear explanation for the higher levels of this antimicrobial protein found in psoriasis than in AD." (PMID 36902728, 2023). "STAT3 mediates the signal of most cytokines that are involved in psoriasis pathogenesis, including the IL-23/IL-17/IL-22 axis." (PMID 37762217, 2023). "IL-23 promotes the survival and maintenance of Th17 cells, which produce IL-17, IL-22 and other inflammatory effector cytokines involved in psoriasis." (PMID 37662940, 2023). "Early in the psoriatic cascade, IFN-γ is capable of activating antigen-presenting cells (APCs) and keratinocytes to generate IL-22 and IL-1β, therefore enhancing cytokine storms in psoriasis." (PMID 37942312, 2023). "Next, we compared the phenotypes of IFNγ-producing or IL-22-producing CD1a-reactive T cells from healthy and psoriasis." (PMID 37267382, 2023).